FABP1 (fatty acid binding protein 1)
Diseases named in the same sentence as FABP1 in open-access papers (continued):
Sharing a sentence is not in itself a finding about the gene and the disease.
tumor (59 papers, 2004 to 2025). "Fatty acid binding protein 1 (FABP1) is overexpressed in various tumors and is closely associated with tumor progression." (PMID 40161377, 2025). "FABP1 deficiency in TAMs reduced tumor growth, invasion, and migration in vitro, highlighting its role in enhancing cancer cell proliferation and aggressiveness." (PMID 41378310, 2025). "FABP1 supports tumor progression by maintaining the M2 phenotype of tumor-associated macrophages (TAMs), which is associated with immune suppression and cancer progression." (PMID 41378310, 2025). "Within 84 MSI tumors, reduced FABP1 expression was weakly associated with L0 status (p = 0.0203) and tumor location in the right colon (p = 0.0023)." (PMID 35951102, 2022). "Within 1067 MSS tumors, reduced FABP1 expression was weakly associated with right-sided tumor location (p = 0.0372)." (PMID 35951102, 2022). "A reduced survival rate and increased tumor size are linked to low FABP1 expression." (PMID 39984452, 2025). "Interestingly, the proportion of cells within cluster 0, which expressed genes characteristic of “traditional” resident AMs, such as Fabp1 and Ear1, was diminished in the tumor-associated AMs." (PMID 41567211, 2025). "First, the Fabp1-Cre transgene is activated early during embryogenesis and remains active throughout the life of the animal, so theoretically the expression pattern could change and cause a previously uni-ancestral tumor to become heterogeneous." (PMID 26919712, 2016). "Conversely, gene expressions previously linked to tumor cell differentiation and favorable outcome, such as SLC26A3, PIGR, CKB and FABP1, were highly expressed in GPA33-high cancer cells." (PMID 39472498, 2025). "Harvested LNs from mice injected with FABP1-KO cells had larger tumor volumes and higher tumor weights." (PMID 40694956, 2025). "In vivo, FABP1 overexpression increased tumour growth, angiogenesis, and lung metastases in murine models, establishing its role as a promoter of tumour progression in HCC cells with high endogenous VEGF-A expression." (PMID 41149452, 2025). "In contrast, CDKN1A upregulation reinforced the cell cycle arrest observed in tumor cells, while FABP1 and BCL2A1 suggest metabolic and apoptotic adjustments in the post-knockdown state." (PMID 41411347, 2025). "By regulating the PPARA signaling pathway, FABP1 influences the uptake of long-chain fatty acids (LCFAs) by tumor cells, thereby altering the tumor microenvironment." (PMID 40717587, 2025). "The expression levels of ANGPTL4 and PPARD were notably higher in tumour tissue, whereas the expression levels of FABP1, SLC27A1 and OLR1 were elevated in normal tissue." (PMID 37556076, 2023). "More importantly, Kaplan–Meier analysis indicated that upregulation of FABP1 was consistently correlated with a worse prognosis, suggesting a tumor promotion role and prognostic value of FABP1 in GC." (PMID 35799608, 2022). "Constitutive activation of PI3K in Fabp1‐Cre+ mT/mG+ Pik3ca*+ApcMin/+ mice resulted in increased tumor number compared to littermate controls (17.3 ± 2.1 vs. 7.2 ± 4.7, respectively)." (PMID 34245130, 2022). "Our data provide a comprehensive overview on the prevalence and intensity of FABP1 immunostaining across a large variety of human tumor entities." (PMID 35951102, 2022). "The administration of this natural product inhibited tumor growth by downregulating PPARα, PPARγ, FABP1, FABP4, and FABP5." (PMID 36296934, 2022). "Overall, 24 (16%) of 150 tumor categories showed detectable FABP1 expression with 17 (11%) tumor categories including at least one case with strong positivity." (PMID 35951102, 2022). "FABP1 positivity was found in 24 of 150 tumor categories, including 17 tumor categories with at least 1 strongly positive case." (PMID 35951102, 2022). "That low FABP1 expression was strongly linked to high-grade, MSI, and right-sided tumor location but unrelated to pT and pN stage is consistent with the results of two earlier studies." (PMID 35951102, 2022).
tumor (continued). "Three epithelial cell clusters (Epi_KRT19, Epi_STMN1, Epi_FABP1) were almost only presented in tumor tissues." (PMID 35087839, 2021). "Patients with high expression of FABP1 in adjacent tumor tissues were more likely to have longer survival times." (PMID 34056002, 2021). "Fatty acid transporter proteins (CD36, Fabp1, Slc27a4) mediate the uptake of fatty acids and were reported to be highly expressed in cancer cells and to function in tumor growth." (PMID 32156004, 2020). "FABP1 expression in GC cells inhibits tumor metastasis to LNs in vivo." (PMID 40694956, 2025). "We also observed temporal changes in other key genes: lipid metabolism-associated genes such as APOA4, FABP1, and FABP2 were upregulated over time, which is consistent with reports that excess lipids promote tumor cell proliferation, colonization, and metastasis." (PMID 41009818, 2025). "FABP1 primarily affects lipid homeostasis in tumor metabolism." (PMID 40717587, 2025). "The resulting disruption of the FABP1–PPARγ feedback loop may contribute to the distinct immune microenvironment of MSI tumours." (PMID 41149452, 2025). "In vitro experiments indicated that interferon gamma (IFNγ), a key immune cytokine in MSI tumours, downregulates FABP1 expression, while activation of PPARγ (with rosiglitazone) can restore it, suggesting a regulatory loop influenced by inflammatory signalling." (PMID 41149452, 2025). "Fatty acid binding protein (FABP1) might play an important role in fatty acid metabolism and is overexpressed in various cancers and promotes tumor angiogenesis and migration." (PMID 38737262, 2024). "Tumor cells had a higher expression of FABP1 than CD8+ T cells in the TISCH database." (PMID 38460179, 2024). "Conversely, FABP1+ tumor cells primarily exhibited enrichment in KRAS_SIGNALING_DN." (PMID 38913193, 2024). "Furthermore, we examined the expression levels of ACADM, FASN, ACC1, ELOVL5, and FABP1 in primary tumor tissues and TD tissues through IHC methods." (PMID 39495391, 2024). "Thus, the increased expression of FABP1 in the tumor leading edge of liver invasion implies the pathological function associated with the malignant transformation of the disease." (PMID 38617005, 2024). "FABP1 may play a role in inhibiting the cytotoxicity of CD8+ T lymphocytes that mediate anti-tumor immunity in the tumor immune microenvironment at the invasion front of the liver." (PMID 38617005, 2024). "Downregulation of FABP1 was correlated with tumor differentiation and intratumoral inflammation." (PMID 31143113, 2019). "Additionally, studies have shown that FABP1 expression is reduced in CRC and is associated with histologic grade, microsatellite instability (MSI), and tumor location in the right side of the colon (P < 0.0001 each), and absence of BRAF V600E mutations (P = 0.001)." (PMID 40717587, 2025). "Notably, the hypoxia/glycolysis signature contains intestinal differentiation markers (e.g., TFF3, FABP1, KRT19), indicating an association of distinct metabolic states with tumor cell differentiation and proliferation, as recently described for the normal intestinal crypt." (PMID 33806447, 2021). "Targeting the FABP1-PLG-PLAT axis inhibits fatty acid metabolic reprogramming and tumor angiogenesis by inhibiting fatty acid binding protein 1 (FABP1) and its downstream plasminogen (PLG) - tissue plasminogen activator (PLAT) signaling pathway." (PMID 41281744, 2025). "Tumor-specific deep crypt secretory cells (tDCS, cluster 10) demonstrated elevated expression of TFF1, FABP1, CKB, PRAP1, IL32, GPRC5A, and SOD3, and were consistent with secretory lineage plasticity and immune or stress-associated signaling." (PMID 41282138, 2025). "Given that FABP1 acts as an essential transport to mediate fat acid translocation and lipid metabolism in cancers, we speculate the same function most likely played by FABP1during liver invasion, where highly proliferated tumor cells disseminate and develop liver colonization." (PMID 38617005, 2024).
tumor (continued). "Although an earlier study shows that FABP1 was overexpressed in HCC tissues compared to adjacent liver tissues, another study found that FABP1 is dysregulated in HCC and that patients with low FABP1 expression have a lower degree of tumor differentiation." (PMID 34056002, 2021). "In agreement with a potential cooperative role for both FABP1 and LCN2, previous work has identified FABP1 as a marker for circulating tumor cells (CTCs) in patients with advanced stage cancers." (PMID 31105883, 2019). "This analysis showed down-regulated target gene (CXCL12, FABP1, MUC2 and PDCD4) expression in tumour compared to normal tissues, in keeping with their documented tumour suppressor functions, when using the larger set of samples." (PMID 20122155, 2010). "Low expression was observed for FABP1 (spot 5105) in both the central and the peripheral part of the tumor compared with the non-involved part." (PMID 34563043, 2021). "In addition, liver FABP1 interacts with VEGFR2 in HCC, further activating specific pathways, and results in VEGF-A upregulation, thereby promoting angiogenesis and tumor migration." (PMID 34685761, 2021). "Bioinformatics analysis showed that TRIB3 and FABP1 may interact with CEACAM5, PRAP1, GABRP, and THBS4, and affect tumor immune microenvironment by regulating immune cells, and participate in the development and progression of GC." (PMID 34957220, 2021). "In conclusion, we speculate that FABP1 in the HCC microenvironment may regulate the distribution of fatty acids by freely entering and exiting HCC cells, thereby regulating tumor progression." (PMID 34056002, 2021). "TRIB3 and FABP1 may interact with CEACAM5, PRAP1, GABRP and THBS4, and affect tumor immune microenvironment by regulating immune cells, and participate in the development and progression of GC." (PMID 34957220, 2021). "FABP1 and fatty acid expression in HCC that is downregulated might be due to the significant enhancement of de novo fatty acid synthesis in tumor cells." (PMID 34056002, 2021). "However, the expression of FABP1 was not significantly correlated with clinical-pathological features such as age, gender, tumor size, histopathological type, lymph node positive, TNM stage, and HER2 positive." (PMID 35799608, 2022). "FABP1 had not been reported to be related to CD4+ T cells, but it could affect the function of tumor-associated macrophages by participating in tumor internal metabolic pathways, and thereby exerting anti-tumor effects." (PMID 34957220, 2021). "Thus, FABP1 has been found to increase tumor angiogenesis in hepatocarcinoma by upregulation of VEGF, and FABP4 was shown to enhance cancer aggressiveness in different tumor entities such as myeloid leukemia, prostate and breast cancer." (PMID 31143113, 2019). "Western blotting revealed that FASN protein expression was elevated in CRC tissues, while real-time PCR and Western blotting indicated that FABP1, CD36 and Caveolin-1 mRNA and protein levels were reduced in CRC, potentially due to the reduced availability of exogenous lipids for the tumor." (PMID 28938608, 2017). "Four spots were found with low expression in the central part of the tumor compared to the non-involved part, including MYL6 (spot 0210), spot 2305, spot 4807 and FABP1 (spot 5105)." (PMID 34563043, 2021). "Proteins that were perturbed in expression level in the peripheral or in the central part of the tumor as compared with the non-involved part included S100A11, HNRNPF, HNRNPH1 or HNRNPH2, GSTP1, PKM and FABP1." (PMID 34563043, 2021). "However, expression levels of FABP1, CD36, IRS1, THBS1, and TGFB1 did not significantly differ in various tumor stages." (PMID 36193307, 2022).
tumor (continued). "However, mRNA expression levels of FABP1, FABP2, FABP5, FABP6, FABP7, FABP9, or FABP12 did not significantly differ in different tumor stages in CRC patients." (PMID 34680577, 2021).
cancer (39 papers, 2004 to 2025). A tumor composed of atypical neoplastic, often pleomorphic cells that invade other tissues. "In the up-regulated DEGs enriched in the PPAR signaling pathway, fatty acid binding protein 1 (FABP1) that was appreciated to mediate cancer lipid metabolism had raised our particular attention." (PMID 38617005, 2024). "First, it remains to be determined how loss of PGAM5 interferes with FABP1 expression and how the PGAM5 and FABP1 pathways converge to impart a pro-cancer survival benefit in HCC." (PMID 37835490, 2023). "We analyzed the differential expression of TRIB3 and FABP1 in different disease groups as well as in the cancer and adjacent tissues." (PMID 34957220, 2021). "FABP1 also inhibits epithelial–mesenchymal transition in different ways, thereby inhibiting cancer infiltration and metastasis in ccRCCs." (PMID 33015999, 2020). "These collective findings suggest that FABP1-targeted cancer therapies may require context-dependent, multimodal intervention strategies." (PMID 40694956, 2025). "The expression level of FABP1 can be used for cancer diagnosis and prognostic assessment." (PMID 40717587, 2025). "Moreover, following ASO treatment, tissue‐specific CD8+ T cells, and primary cancer cells showed similar FABP1 expression." (PMID 38460179, 2024). "First, we tested the expression of FABP1 in primary cancer cells and tissue‐specific CD8+ T cells." (PMID 38460179, 2024). "Although FABP1 has been intensively studied in a number of human cancers, its pathological role in GBC and its predictive potential for disease outcome remain unknown." (PMID 38617005, 2024). "Genes with no significant expression in the majority of the normal donors and exhibiting expression patterns associated with a particular cancer type were 16, among them AGR2, S100A14, S100A16, and FABP1 identified as those with the highest discrimination power between cases with cancers and donors." (PMID 36428760, 2022). "FABP1 expression was observed throughout cancer development." (PMID 31737124, 2019). "In particular, coupling of energy metabolism between CAMs and cancer cells may be mediated by fatty acid binding proteins, such as FABP1 and FABP3, which were also upregulated in hypoxic CAMs." (PMID 30813438, 2019). "The most central protein, fatty acid-binding protein 1 (FABP1), was found to be upregulated in cancer tissues with low GPx3 expression." (PMID 38732573, 2024). "The protein biomarkers identified, such as CK7, CDH17, MLPH, FABP1, and NARR, can be used for differential diagnosis between the two cancers in primary healthcare institutions using IHC staining." (PMID 38608841, 2024). "Differential expression analyses comparing cancer areas of rHGP and dHGP revealed established CRC cell markers, such as FABP1, CEACAM5, CLDN3, EPCAM and S100A10 in the rHGP (Supplementary Spreadsheet 1)." (PMID 36691028, 2023). "Regarding the lipid metabolism, an upregulation of FABP1 in HCC was shown to stimulate angiogenesis and cancer cell migration, while PLIN2 overexpression is observed in many cancers and is suggested to have a role in tumorigenesis, for example, by favoring adaptation to hypoxia." (PMID 36139435, 2022). "Immunofluorescent staining of primary CRC sections with antibodies directed against the stem cell marker OLFM4, the proliferation marker KI67, and the differentiation markers TFF3 and FABP1 revealed cell heterogeneity, but not how cancer cells in the tissue are related to each other (Fig EV4)." (PMID 34409732, 2021).
kidney diseases (29 papers, 2013 to 2025). "Interestingly, recent studies have shown that urinary FABP1 in humans would be a useful clinical marker for prediction and monitoring of the progression of renal diseases." (PMID 24278421, 2013). "More importantly, FABP1 has been identify patients at risk of developing kidney diseases, including AKI and CKD, and to protect the kidneys in the course of kidney disease, as detailed in our previously published review 14; hence, we considered FABP1 as a hub gene in the turquoise module." (PMID 36147466, 2022). "However, the mechanism of action of FABP1 in renal diseases is unclear." (PMID 32038102, 2020). "Previous studies have also demonstrated that FABP1 can play an important role in injury and repair processes in the kidneys, and that the monitoring of urine FABP1 concentration may make it possible to predict the occurrence and severity of various renal diseases 19,23." (PMID 32922199, 2020). "Importantly, FABP1 has a protective role against AKI and CKD during the course of kidney disease." (PMID 36147466, 2022).
metabolic disease (10 papers, 2012 to 2025). A congenital disorder (due to inherited enzyme abnormality) or acquired (due to failure of a metabolically important organ) disorder resulting from an abnormal metabolic process. "A role for FABP1 in metabolic disease is also suggested, albeit indirectly, by the presence of a single-nucleotide polymorphism (SNP) in the coding region of human FABP1 that results in a threonine to alanine replacement (T94A)." (PMID 37207357, 2023). "Increasing FABP1 expression in HepG2 cells results in increased uptake of radiolabeled oleic acid by 38% and 78%, respectively, and downregulation of FABP1 levels has a therapeutic effect in metabolic diseases." (PMID 38791126, 2024). "Liver-type fatty acid-binding protein (FABP1) contributes to metabolic disorders." (PMID 36277716, 2022). "A recent study demonstrated that dark tea extract could ameliorate glycolipid metabolism disorders in db/db mice by mediating the expression of key factors in the PPAR signaling pathway, such as Ehhadh and Fabp1." (PMID 40431433, 2025). "Also, the increase of GSTA1 by bicyclol treatment resulted in a decrease in FABP1 levels and an improvement of the disease, highlighting a possible mechanism of action of GSTA1 in metabolic diseases." (PMID 38791126, 2024).
infection (9 papers, 2010 to 2025). The state of being infected such as from the introduction of a foreign agent such as serum, vaccine, antigenic substance or organism. "A loss in host defenses due to decreased energy utilization from dysregulated fatty acid metabolism and the protection from oxidative stress afforded by Fabp1 subverts its role in resistance to infection." (PMID 38107402, 2023). "Meanwhile, after infection of the Huh-7 cells with FABP1 RNAi, fatty acid-induced lipid content was reduced." (PMID 34056002, 2021). "Notably, after 24 h of infection, Fabp1, the transporter of long-chain fatty acids (13–21 carbons in the aliphatic chain), was strongly up-regulated in M0 and M1-like BMDM infected with VBNC, but not by uninfected M1-BMDM." (PMID 39714095, 2025). "In addition, VBNC-BMDM infection up-regulated Fabp1 and Fabp2 and down-regulated Fabp4." (PMID 39714095, 2025). "This suggests that FABP1 may help modulate the liver's reaction to infection-related stress." (PMID 40446677, 2025). "There was an increase in MAST4, FABP1, and KLKB1 levels that lasted until 18 h after LASV infection, whereas increased concentrations of IGFBP3 lasted until 48 h after infection." (PMID 35337059, 2022).
adenocarcinoma (3 papers, 2022 to 2024). A common cancer characterized by the presence of malignant glandular cells. "It is evident that elevated FABP1 expression in the DI region is not limited to adenocarcinoma subtype of GBC; rather, it is also observed in other histological subtypes of GBC." (PMID 38617005, 2024). "Meanwhile, FABP1 staining was not seen in 169 primary adenocarcinomas of the lung." (PMID 38608841, 2024). "FABP1 staining was not seen in 169 primary adenocarcinomas of the lung." (PMID 35951102, 2022).
hematological disorders (1 paper, 2019). "FABP1 could be involved in CMDs risk assessment and perhaps link psoriasis with hematological disorders." (PMID 30993401, 2019).